CD14 (CD14 molecule)
Diseases named in the same sentence as CD14 in open-access papers (continued):
Sharing a sentence is not in itself a finding about the gene and the disease.
infection (continued). "As expected, lenti-shTGFBI infection of THP-1 cells resulted in significant downregulation of TGFBI expression and impaired the PMA-induced macrophage-like differentiation as revealed by the decreased mRNA expression of differentiation markers (CD11b and CD14) compared with the lenti-ctrl infection." (PMID 33128580, 2021). "In our present study, we confirmed that TLR signaling-related genes, including Tlr4, Nfkb, Myd88, Cd14, Il6 and Tnf, are gradually increased in the AP mouse model following induction of the infection and become highly expressed when lesion formation accompanied by bone destruction is established." (PMID 33510341, 2021). "Parallel infection of the unsorted DCs showed that all Npos cells were CD14–." (PMID 34177915, 2021). "In those cases, the loss of CD14 was assumed to be caused by infection-induced apoptosis but not virus-specific regulation." (PMID 34177915, 2021). "The proportion of CD14+ cells decreased significantly in the inoculated cultures compared with the mock-inoculated ones (30.7 ± 5.0% versus 18.2 ± 3.7%, respectively, p<0.05; 33.2 ± 2.8% before infection)." (PMID 34177915, 2021). "Of note, the infection resulted in the loss of CD14 expression, as deduced from the decrease in the proportion of CD14+ cells in infected cultures and the fact that labeling of PRRSV N protein was mostly found in CD14– cells, while, when sorted, CD14– cells were refractory to the infection." (PMID 34177915, 2021). "Subsequent follow-up analysis found that circulating CD14+HLA-DRlo/neg MDSC frequency was significantly lower post-infection compared to the levels observed during infection, however it was still significantly higher 4-10 days post-infection for severe patients compared to HCs." (PMID 33640878, 2021). "By 25 days post-infection, there was a significant decrease in the overall monocyte/Mφ population in the blood (CD14+CD11b+CD11c+), and a decrease in varying monocyte/Mφ subpopulations throughout all tissues (CD14+CD11b+CD11c-, CD14+CD11b-CD11c-)." (PMID 34106915, 2021). "The suppression of CD14 is speculated to be required to weaken the damage response and to favor a strong defense in response to infection." (PMID 33072626, 2020). "In addition, infection with P. vivax induced expression and cleavage of caspase-8 in circulating CD14+ monocytes." (PMID 32929083, 2020). "First, CD14+ cells displayed higher infection by T. cruzi trypomastigotes than CD14- cells." (PMID 33146244, 2020). "Sixty minutes of exposure to UV light resulted in greater than 10-fold reduction in GFP expression, a surrogate for TB40/E-5 infection, in UV-infected versus live virus–infected CD14+/16− monocytes, while 10 min of exposure resulted in twofold decrease in GFP expression." (PMID 32494628, 2020). "Classical monocytes (CD14+CD16-) expressing Ki-67 increased after infection in all animals." (PMID 32946524, 2020). "CD14+ monocytes also present cytotoxic activity during infection and cancers." (PMID 32276581, 2020). "We therefore hypothesized that TLR2/CD14-dependent CME facilitates DENV entry to establish infection." (PMID 32576819, 2020). "We confirmed productive infection in both CD14+ monocytes and CD19+ B cells as we could detect DENV NS3 protein." (PMID 33643283, 2020). "Therefore, such CD14 molecule will provide an optimal and effective immune response against infection." (PMID 31963925, 2020). "Our inability to detect this subset could be due to its low frequency compared with the other two monocyte subsets or the fact that expansion of CD14+CD16+ monocytes typically occurs within the first 2 d of infection before dramatically dropping off." (PMID 33067399, 2020). "Furthermore, we observed that CD14- monocytes showed a more activated profile upon in vitro infection with T. cruzi than CD14+ monocytes." (PMID 33146244, 2020). "Furthermore, on CD14+ CD11b+ cells, PD-L1 expression was increased by infection and more so in hypoxia." (PMID 32091388, 2020).
infection (continued). "IAV nucleoprotein 1 (NP1) was readily detectable in particular in lung CD14+ cells but also, with lower expression, in NK cells and T cells in blood and lung after 24 h of infection at a MOI of 0.5, indicating that subsets of these cell populations were productively infected." (PMID 31156653, 2019). "We also analyzed the effect of cellular differentiation on IFI16 expression following infection in mature dendritic cells derived by treating ex vivo CD14+ monocytes with granulocyte-macrophage colony-stimulating factor (GM-CSF)/interleukin-4 (IL-4)/lipopolysaccharide (LPS)." (PMID 31796538, 2019). "In contrast, monocytes infected with the B. pertussis WT or the B. pertussis AC+ PT− bacteria expressed increased CD14 levels, showing that infection by B. pertussis strains secreting active CyaA toxin hampered M-CSF-driven downregulation of the human monocyte marker CD14." (PMID 31551332, 2019). "We hypothesize that this, together with the early loss of cells of CD14++CD16+ cells, may contribute to the increased susceptibility to infection which can complicate both AAH and AP." (PMID 31507587, 2019). "Indeed, reduced levels of CD14 upon infection by Porhymonas gingivalis and Pseudomonas aeruginosa have been reported as being related with hyporesponsiveness to bacterial challenge." (PMID 31024862, 2019). "A milder effect is observed in CD14+ monocytes after infection (1.5–2.0-fold induction)." (PMID 30610612, 2019). "Both hepatocytes and liver macrophages synthesize soluble factors, such as complement and soluble pattern recognition receptors (e.g., lipopolysaccharide binding protein, soluble CD14) that are essential for effective systemic immune responses and resistance to infection." (PMID 30873165, 2019). "The lower abundance of CD14 mRNA observed upon infection by R. conorii might, therefore, affect LPS signaling and downstream pathways." (PMID 31024862, 2019). "The decrease in infection was inspected not due to LPS mediated release of cytokines but due to blockage of CD14 and its associated cell surface molecules by LPS." (PMID 31489877, 2019). "The dynamics of the CD14 cells recruitment at the peritoneal cavity displayed a decreasing trend during the early stage and was significantly decreased at the chronic stage of the infection." (PMID 30547823, 2018). "Wild-type T. gondii infection in human CD14+ monocytes from peripheral blood caused IL-1β production, whereas infection by GRA15-KO parasites did not." (PMID 30301855, 2018). "However, sorted CD14+ myeloid cells isolated 20 h post-infection from 5 HIV-infected cervical explants tested all transmitted HIV to activated CD4+ T cells, while only 1 sample of sorted CD4+ T cells did." (PMID 30532754, 2018). "We previously reported that CD14+ cells are a PBMC subpopulation susceptible to DENV infection in vitro and that they are responsible for the production of inflammatory cytokines during infection." (PMID 29986388, 2018). "ZIKV infectivity of monocytes, T and B cells was assessed at two days post-infection, with intracellularly staining by an anti-E antibody in combination of cell surface staining with CD14, CD3 and CD19 antibodies that identify monocytes, T cells and B cells, respectively." (PMID 30044839, 2018). "Interestingly, we also found a small subpopulation of CD14+ monocytes with distinctly higher expression of previously unreported markers (CCR4, CXCR3, and CCR6) that also associated with the acute phase of infection." (PMID 30150281, 2018). "Pro-inflammatory CD14+CD16+ monocytes play an essential role in infection and inflammation." (PMID 29538412, 2018). "CD14+ monocytes have been reported to be the main targets of ZIKV during infection (6, –, 9)." (PMID 29600283, 2018).
infection (continued). "Analysis of the 366 cells that expressed viral transcripts revealed low expression levels, and as in CD14+ monocytes, the low viral gene expression that we measured in these cells correlated with the expression pattern of the late stage of lytic infection (comparing CD34+ cells to cluster 1)." (PMID 29535194, 2018). "Entry of infected CD14+ CD16+ monocytes may lead to infection of other CNS cells, including macrophages or microglia and astrocytes, and to release of neurotoxic early viral proteins and additional cytokines." (PMID 29066542, 2017). "As soluble CD14 is an acute phase protein introducing bacterial products to leukocytes and other cells at the early stage of an infection, it may prevent lethal side effects of bacterial products at the late phase of an infection." (PMID 28845081, 2017). "Interestingly, differences in the dynamics of CD14+ cells were observed between the persistent-infection and controlled-infection statuses." (PMID 27799331, 2017). "Analysis of CD14-expressing cells revealed a steady increase in CD14+ monocytes during infection." (PMID 28662714, 2017). "Other infection events such as chronic infection of HIV and HBV also result in increased PD-L1 levels on CD14+ monocytes, which may establish an immune tolerant environment to allow for long-term infection." (PMID 29018115, 2017). "However, in granuloma-like structures in which infection was controlled, CD14+ macrophages remained abundant over 4 days after infection, whereas they were reduced when infection persisted." (PMID 27799331, 2017). "Total RNA from control siRNA and NLRP3 siRNA transfected CD14+ monocytes was used for the detection of ZIKV copies at 72 h post-infection, which showed a significantly reduced viral copies in NLRP3 siRNA transfected monocytes as compared to the control siRNA transfected cells." (PMID 29167459, 2017). "Over the course of infection, ExMФ upregulate the tissue macrophage-specific markers, CD169 and MerTK and also exhibit increased expression of macrophage-associated markers such as CD14 and F4/80." (PMID 26938654, 2016). "Interestingly, only C. gingivalis survived within the CD14+ cells, even after 24 hours of infection." (PMID 27383402, 2016). "A transient increase in CD14+CD16+ intermediate monocytes was observed early in infection." (PMID 26982706, 2016). "As infection progresses, the parasite might trigger CD14 and other signaling molecules, inducing the release of both anti-inflammatory and pro-inflammatory molecules, with a persistent absence of specific IFN-γ response being the halmark of classical VL." (PMID 26814478, 2016). "Additionally, infection of primary CD14+ monocytes followed by coculture with MRC5 cells in the presence of the α-gH mAbs demonstrated their ability to block dissemination from fibroblasts to monocytes." (PMID 27966523, 2016). "Furthermore, CD14+ milk cells appear to prevent the in vitro infection of the intestinal epithelium with S. typhimurium." (PMID 25806034, 2015). "Importantly, ex vivo infections of primary CD14+ human monocytes with S. aureus Newman and a PVL+ USA 300 strain revealed that LukAB is indeed responsible for cell death and FLICA-1 activation post-phagocytosis in human monocytes." (PMID 26069969, 2015). "Down-regulation of CDC25A induced CD11b and CD14 expression 3 and 6 days after infection respectively, while CD15 expression was decreased, confirming the data obtained by pharmacological inhibition and further arguing for the implication of CDC25A in the differentiation process." (PMID 26515730, 2015). "TLR2+CD14+ cell population was up-regulated upon DV infection on day 3 post-infection." (PMID 26226614, 2015). "The CD14 antigen is a glycosylphosphatidylinositol (GPI)-anchored receptor known to serve as a co-receptor for several TLRs that were significantly up-regulated in M. fortis after infection with S. japonicum." (PMID 24886088, 2014).
infection (continued). "Using CD14 (+) monocytes cultured under these specific conditions resulted in the presence of the HCMV genome in the absence of immediate early gene expression after approximately 18 days post infection." (PMID 23717203, 2013). "Finally, this myeloid infection allows infection of circulating leukocytes, such as CD14+ cells in the case of BoHV-4." (PMID 24204281, 2013). "This is unlikely since infection of CD14 (+) monocytes with UV-inactivated virus indicated that, although all latent RNAs were detected at 1 hr post infection due to apparent packaging in virions, we were unable to detect these transcripts at 5 or 10 days post infection." (PMID 23717203, 2013). "At 18 days post infection of CD14 (+) monocytes the transcriptome analysis showed that only a subset of viral-encoded RNAs were present in latently infected cells and confirmed that neither immediate early IE2 or IE1 mRNAs were expressed, nor were any other immediate early transcripts detected." (PMID 23717203, 2013). "Hence we infected CD14 (+) monocytes with UV inactivated virus and performed qPCR at 5 and 10 days post infection." (PMID 23717203, 2013). "Infection of mice with as few as 102 CFU resulted in increased mortality in CD14−/− and TLR2−/− mice, though only the latter reached statistical significance wherein the MTD was 18 days versus >21 and the percentage surviving was 50% versus 100% for control animals." (PMID 23554897, 2013). "However, infection of PBMCs with USA300, USA300Δhla, USA300Δhla comp, and USA300ΔsaeR/S at an MOI of 5 and 10 demonstrated Hla significantly enhances CD14+ PBMC plasma membrane permeability at 6 hours post-infection." (PMID 22574180, 2012). "Nevertheless, after infection of whole PBMCs for two days, a small population of CD14+CD16- monocytes could still be observed." (PMID 22574162, 2012). "In the present study, we found that in vitro infection of freshly isolated, undifferentiated CD14+ primary human monocytes with Leishmania consistently led to maturation into macrophages and to higher cell numbers over time as compared to uninfected control cells." (PMID 22496656, 2012). "Moreover, there was a ∼3–4 fold decrease in the level of viral copy numbers in FIX-ΔLUNA CD14+ cells after differentiation when compared to infection with FIX-WT (p<0.01) or FIX-Rev (p<0.01)." (PMID 23300789, 2012). "Our study is the first one, which quantified APOBEC3 mRNA in the context of an immunodeficiency virus infection not only in whole PBMC, but also in leukocyte subsets susceptible to infection such as CD4+ T-cells and CD14+ monocytes as well as in the lymph nodes as major virus replication sites." (PMID 21955401, 2011). "However, the CD14+/TNF-α+ lung cell population at 16 weeks of infection was moderately higher than that of 4 and 8 weeks." (PMID 22645653, 2011). "Furthermore, this study confirms the previous findings of the role of CD-14 associated molecules and clathrin mediated endocytosis in DENV entry in the host cells and establishing the infection." (PMID 22140591, 2011). "Finally, after S. suis invasion of the central nervous system, transcriptional activation of TLR2, TLR3 and CD14 has been observed in a mouse model of infection." (PMID 21635729, 2011). "However, compared to wt mice, TLR2-/- mice presented even a reduced influx, CD14-/- mice had an increased influx and TLR2-/-/CD14-/- mice had similar leukocyte numbers as wt mice at 12 h after infection." (PMID 17428319, 2007). "The lines for wt C57BL/6J and the CD14-/- mice overlapped on day 4 and 7 post-infection." (PMID 16995947, 2006). "The increased proportions of T‐cells (CD4+ central memory, naive) and NK cells in mild and severe samples suggest an enhanced adaptive immune response as infection progresses, while the reduced abundance of Monocyte:CD14+ and Platelets in severe cases may reflect immune exhaustion or tissue damage." (PMID 40910395, 2025).
infection (continued). "Interestingly, the protein encoded by SERPING1 is associated with regulatory inhibition of the complement system and may be upregulated in CD14 + monocytes from PLWH as a mechanism of limiting infection." (PMID 41345807, 2025). "IFN-enriched CD4+ T and CD14+ monocyte subsets, previously characterized in dogs as tissue-patrolling or inflammatory responders, may constitute a surveillance network capable of rapid activation under stress or infection." (PMID 41488614, 2025). "Moreover, GFP expression was essentially absent in cells exposed to HIV-1 BaL-GFP in the presence of the reverse transcriptase inhibitor AZT, thus, demonstrating the specificity of detected GFP expression as a marker for de novo infection of both CD14+ cells and CD4+ T cells." (PMID 39872519, 2024). "Therefore, the increase rate of DN infection that we observed in whole blood may represent infected, CL in which CD14 is lost." (PMID 35744760, 2022). "Microarray results showed that mRNA and CD14 (glycolipid-anchored membrane glycoprotein expressed in cells of the myelomonocyte lineage, such as macrophages) levels increased during the early stages of infection, with protein levels decreasing 15 days after infection." (PMID 36359026, 2022). "cDC1 and cDC2 were not susceptible to 3267 infection, but a fraction of CD14+ DCs were infected." (PMID 34177915, 2021). "Some of them were atypical subsets that could be key to understanding the infection, such as the double-positive CD14+CD3+ subset observed within the ‘live singlet’ events gate, a T-cell/monocyte complex described in diseases where the immune system is disturbed." (PMID 35069575, 2021). "However, we observed an increase in frequency of CD14 expressing cells after both infections." (PMID 31539406, 2019). "To assess whether similar signaling pathways operated in human monocytes encountering live S. aureus, we first determined TNFα and IFN-I production from both the human monocytic cell line THP-1 and from blood-derived CD14+ monocytes in response to infection with S. aureus." (PMID 31558608, 2019). "A similar trend was observed regarding CD16 expression during infection (63.3% vs 45.4% of macrophages expressing CD16) indicating that these mature macrophages display an altered phenotype during SIV infection with a higher percentage expressing CD14 and CD16." (PMID 29466439, 2018). "Thus, CD14+ myeloid cells sorted from infected cervical explants 1 day after infection are more efficient at transmitting infectious HIV to activated CD4+ T cells than cervical CD4 T cells, suggesting an important role of myeloid cell capture early in HIV transmission." (PMID 30532754, 2018). "Thus, CD14+Siglec-1hiCD4+MDM were less permissive to infection." (PMID 29123518, 2017). "However, we found that that CD14 was low-abundant, which is in contrast to a previous study in mastitic cows which reported elevated levels of CD14 either in serum or milk whey following intramammary infection with S. aureus." (PMID 29283389, 2017). "However, during the initial stages of infection, 1,25(OH)2D3 may protect against bacterial infections by augmenting CD14 expression, as shown by our data from LPS-stimulated PBMCs." (PMID 27973447, 2016). "However, CD14+ cells are efficient activators of memory T cells suggesting a role in local tissue responses, particularly during secondary infection when DENV-specific T cells may be present in the skin." (PMID 25474532, 2014). "In addition to these resident macrophage populations that arise under steady-state conditions and at specific time points, CD14++CD16− classical monocytes or their GR1+/Ly6Chigh counterparts in mice can recruit to sites of infection or injury and differentiate into macrophages." (PMID 25232355, 2014).